GSK3A (glycogen synthase kinase 3 alpha)
Diseases named in the same sentence as GSK3A in open-access papers (continued):
Sharing a sentence is not in itself a finding about the gene and the disease.
glioblastoma (3 papers, 2019 to 2025). The most malignant astrocytic tumor (WHO grade IV). "Blockage of GSK-3α/β pathways or direct suppression of GSK-3α/β expression significantly led to reduced expression of TRANK1 in U-251 human glioblastoma cells." (PMID 34992606, 2021). "MA inhibited the activation of tyrosine phosphorylation of GSK-3α(Tyr 279)/β(Tyr 216), and affected the translocation of GSK3 kinase, β-catenin, and pERK1/2 to the nucleus in glioblastoma cells." (PMID 39863145, 2025).
glomerulosclerosis (3 papers, 2019 to 2025). A hardening of the kidney glomerulus caused by scarring of the blood vessels. "Combined knockout (KO) of both GSK3α and GSK3β specifically in glomerular podocytes in embryonic or adult mice caused severe podocyte injury, glomerulosclerosis, and heavy proteinuria." (PMID 35166234, 2022).
liver cancer (3 papers, 2019 to 2024). An epithelial or non-epithelial malignant neoplasm that arises from the liver. "Consistently, data from Human Protein Atlas showed that liver cancer and endometrial cancer patients with higher levels of GSK3α expression exhibited worse overall survival times than their low-expression counterparts." (PMID 35292059, 2022). "Lanatoside C displayed a potent inhibitory effect on key target proteins of Wnt signaling, i.e., GSK-3α and β-catenin in Lanatoside C treated breast, lung, and liver cancer cells." (PMID 31783627, 2019).
male infertility (3 papers, 2015 to 2019). The inability of the male to effect fertilization of an ovum after a specified period of unprotected intercourse. "gsk3a has been confirmed to be essential for normal sperm motility, and loss of gsk3a led to male infertility due to the decrease in sperm motility." (PMID 29232857, 2017). "Knockout of GSK3α in post-meiotic testicular germ cells, using the Cre-Lox strategy, also results in male infertility." (PMID 31921853, 2019). "We have recently shown that GSK3α isoform has an essential role in male reproduction and its ablation from testis results in abnormal sperm motility resulting in male infertility." (PMID 26569399, 2015). "It was recently shown that Gsk3α null mice exhibit male infertility." (PMID 31921853, 2019).
multiple myeloma (3 papers, 2010 to 2020). "In this study, we have investigated GSK-3α and GSK-3β function in multiple myeloma (MM)." (PMID 20920357, 2010).
oral cancer (3 papers, 2015 to 2024). "The expression of GSK3β was significantly higher relative to GSK3α indicating the greater role of the β isoform in oral cancer." (PMID 25645517, 2015). "The activity of GSK3α/β was also assessed by detecting its site-specific phosphorylation in various oral cancer samples, more elaborately in oral tongue SCC (OTSCC) samples." (PMID 25645517, 2015). "Further investigation is warranted to investigate the mechanism of down regulation of GSK3α/β in certain fractions of oral cancer." (PMID 25645517, 2015). "Among various types of oral cancers, OSCC (of the lip and tongue) showed elevated expression of GSK3α/β, and the expression was correlated with disease progression." (PMID 25645517, 2015).
type 2 diabetes (3 papers, 2013 to 2025). "Therefore, the present study indicates that elevated expression of PEPCK, G6Pase, and GSK3α may be implicated in etiology of glucose intolerance and type 2 diabetes induced by long-term heavy alcohol consumption." (PMID 23819126, 2013). "The GSK3α is a highly important kinase in liver and can be used to treat type 2 diabetes by inhibiting kinase activity." (PMID 40368138, 2025). "This hypothesis is further supported by the fact that GSK-3α/β expression and activity are significantly elevated in Type 2 diabetes mellitus (T2DM) patients." (PMID 35159367, 2022).
viral infection (3 papers, 2017 to 2025). "In our immunofluorescence screening data, only GSK3A showed a proviral potential on HAdV-B7 expression, which significantly increased the viral infection rate in HeLa cells." (PMID 40537285, 2025). "We previously showed that GSK-3α/β inactivation with siRNAs and SMIs specifically downregulates PD-1 expression which leads to enhanced CD8+ CTL function and clearance of viral infections and cancer." (PMID 29312284, 2017). "Recently, we reported that the inactivation of GSK-3α/β with siRNAs and drug inhibitors specifically downregulate PD-1 expression for enhanced CD8+ CTL function and clearance of tumors and viral infections." (PMID 29312284, 2017). "After viral infection of INS-1 832/13 cells, we validated their efficacy by showing that both GSK3β-specific shRNA sequences efficiently decreased mRNA levels of GSK3β, without alterating the levels of GSK3α mRNAs." (PMID 34876563, 2021).
adenoma (2 papers, 2015 to 2019). A neoplasm arising from the epithelium. "More detailed analysis showed that the expression of both GSK3A (0.01-fold with adjusted P < 1 × 10−6) and RHOA (0.35-fold with adjusted P < 0.01) in adenoma patients was significantly lower than those in normal healthy subjects." (PMID 31506480, 2019).
amyloid (2 papers, 2021 to 2025). "Phosphorylation of tau protein by GSK-3β and the protective effect of insulin are well established, while involvement of GSK-3α in amyloid plaque formation is also suggested; thus, its inhibition is clearly connected to the anti-AD effect." (PMID 41226821, 2025). "In addition to tau phosphorylation, these kinases are also involved in APP processing also, e.g., GSK3, especially GSK3α, promotes Aβ formation from APP offering new approach, that inhibition of GSK3α might attenuate amyloid plaques and NFT formation." (PMID 34572312, 2021).
autism (2 papers, 2017 to 2024). Persistent deficits in social interaction and communication and interaction as well as a markedly restricted repertoire of activity and interest as well as repetitive patterns of behavior. "Furthermore, the fragile X mental retardation protein (FMRP) KO mouse model of FXS exhibits increased levels of GSK-3β, whereas mice with active GSK-3α/β isozymes share some autism-related features with FMRP KO mice." (PMID 26738851, 2017).
Bladder Carcinoma (2 papers, 2019 to 2023). "Our phosphoproteomic data and bioinformatic analyses suggest two key activated kinases (GSK3A/B and CDK1) as potential druggable targets for the aggressive subtype of bladder carcinoma." (PMID 31108958, 2019). "Our study reveals GSK3A/B and CDK1 as promising druggable targets for the non-type molecular subtype, which could improve the treatment outcomes for aggressive bladder carcinoma." (PMID 31108958, 2019). "GSK3A/B and CDK1 could be potential druggable targets for the aggressive non-type bladder carcinoma." (PMID 31108958, 2019).
cervical cancer (2 papers, 2024 to 2025). A primary or metastatic malignant neoplasm involving the cervix. "Our group’s previous research has shown that it inhibits the cycle and apoptosis of cervical cancer cells through the AKT/GSK3α signaling pathway." (PMID 39364054, 2024).
colorectal cancer (2 papers, 2014 to 2023). A primary or metastatic malignant neoplasm that affects the colon or rectum. "To define factors that drive dependence toward the GSK3α-dependent proteasomal degradation machinery, we started by inducing a knockdown of GSK3α in Jurkat T-ALL cells as well as in the colorectal cancer (CRC) cell line HCT15." (PMID 37686063, 2023). "Silencing of TESC also significantly attenuated the phosphorylation of glycogen synthase kinase 3 (GSK3) protein isoforms GSK3α and GSKβ and increased levels of E-cadherin expression (unpublished data) in TESC-depleted colorectal cancer cells." (PMID 24811141, 2014). "However, treatment with the elongation inhibitor homoharringtonine failed to rescue cells from GSK3α-mediated cell death upon asparagine depletion in Jurkat T-ALL cells as well as in colorectal cancer cells." (PMID 37686063, 2023).
COVID-19 (2 papers, 2023 to 2025). A disease caused by infection with severe acute respiratory syndrome coronavirus 2. "Further support for the potentially detrimental role of GSK3α/β in the pathogenesis of COVID-19 is provided through studies demonstrating positive effects in patients treated with the GSK3α/β inhibitor lithium." (PMID 37737732, 2023). "Females tend to have better outcomes from COVID-19, and our results showing that GSK3α/β activity, as represented by an increase in phosphorylation, is lower in the hearts of female ferrets compared with males infected with SARS-CoV-2, may provide insight into sex-dependent protection." (PMID 37737732, 2023). "Conversely, silencing of GSK3A and GSK3B drastically reduced the expression of the gene sets that characterize tissue-resident lung alveolar macrophages in COVID-19, with the concomitant silencing of GSK3A and GSK3B again showing a stronger effect." (PMID 40365863, 2025). "This study shows sex differences in stress proteins p62/SQSTM1, ERK1/2, and GSK3α/β, along with innate immunity and inflammation in hearts of ferrets infected with SARS-CoV-2, identifying mechanisms of COVID-19 cardiac injury and cardiac complications of long COVID." (PMID 37737732, 2023).
diabetic cardiomyopathy (2 papers, 2023 to 2025). Diabetic cardiomyopathy is a disorder of the heart muscle in people with diabetes. "Glycogen synthase kinase-3 alpha (GSK-3α) enhances the transcriptional activity of PPARα on lipid uptake and storage-related genes through phosphorylation at the Ser280 site, promoting myocardial lipid accumulation and diabetic cardiomyopathy." (PMID 40734976, 2025). "It would be intriguing to test if there is a link between STIM1 and GSK-3α activity (Figure 5➁), which would provide more insights on the mechanisms by which STIM1 regulates FA metabolism in diabetic cardiomyopathy." (PMID 37685995, 2023).
dyslipidemia (2 papers, 2022 to 2025). "In this study we examine the effect of dyslipidemia on the endothelium and specifically focus on the role of GSK3α/β in this process using Tie2Cre recombinase to selectively ablate GSK3 in ECs." (PMID 36499109, 2022).
epilepsy (2 papers, 2017 to 2025). A brain disorder characterized by episodes of abnormally increased neuronal discharge resulting in transient episodes of sensory or motor neurological dysfunction, or psychic dysfunction. "Considering that cortical neurons, especially the migration of neurons, are quite significant for epilepsy, our predicted gene GSK3A may very probably be epilepsy associated gene." (PMID 28255556, 2017). "Sgk3, Gsk3a, and Stk38, as well as other stress kinases that we found to be overexpressed in the brainstem, such as Map3k13, have been less well-studied in the context of epilepsy." (PMID 41511350, 2025).
Hepatic steatosis (2 papers, 2023 to 2025). Steatosis is a term used to denote lipid accumulation within hepatocytes. "Meanwhile, GSK3α inhibition may be particularly beneficial in alleviating high-fat diet-induced hepatic steatosis by inhibiting de novo adipogenesis and further promoting glycogen storage." (PMID 41515216, 2025).
hepatocellular carcinoma (2 papers, 2023). A malignant tumor that arises from hepatocytes. "EVs isolated from the media of hepatoma cells upregulated pERK1/2 signaling and inhibited GSK3-α/β signaling in LX2 cells whereas LX2-derived EVs caused a moderate increase in pERK1/2 activity in HLE but no other effect was detected." (PMID 37762298, 2023). "In the reciprocal setup, the conditioned media of hepatoma cell lines activated ERK1/2, Akt(T308), and GSK3-α/β but downregulated β-catenin and NF-κB." (PMID 37762298, 2023). "EVs isolated from the conditioned media of both hepatoma cell lines stimulated the pERK1/2 in LX2 cells and promoted the inactivation of GSK3-α/β." (PMID 37762298, 2023).
Infertility (2 papers, 2013 to 2024). "It has been reported that disruption of SPACA1 leads to infertility due to abnormal sperm head shape and abnormal acrosomes in sperm, and GSK3A-deficient mice show bent sperm heads, similar to the phenotype of Ccdc28a−/− mice." (PMID 38597936, 2024). "We concluded that the total deficiency of GSK3α profoundly disturbed the morphology and the motility of sperm, causing infertility of GSK3α-deficient males, in contrast to normal fertility of neuron-specific GSK3α-deficient male mice." (PMID 23705847, 2013).
ischemia (2 papers, 2021 to 2025). A hypoperfusion of the BLOOD through an organ or tissue caused by a PATHOLOGIC CONSTRICTION or obstruction of its BLOOD VESSELS, or an absence of BLOOD CIRCULATION. "Previous studies from our group have shown that GSK-3α activity is reduced in response to ischemia or hypoxia/reoxygenation (H/R)." (PMID 40836599, 2025). "Glycogen synthase kinase-3α (GSK-3α) is a multifunctional kinase that plays roles in the pathogenesis of various cardiac diseases, including ischemia and pressure overload and ischemia-reperfusion-induced injury." (PMID 40836599, 2025). "GSK-3α-mediated miRNA dysregulation may contribute to the pathophysiological changes observed in ischemia-induced cardiac injury." (PMID 40836599, 2025).
left ventricular hypertrophy (2 papers, 2018 to 2019). Enlargement of the LEFT VENTRICLE of the heart. "In a previous study, 2,5-dimethylcelecoxib (DM-celecoxib) was found to activate GSK-3α and β by inhibiting Akt, and to prevent left ventricular hypertrophy and fibrosis." (PMID 30669571, 2019). "In previous study, 2,5-dimethylcelecoxib (DM-celecoxib) can activate GSK-3α and β by inhibiting Akt, to prevent left ventricular hypertrophy and fibrosis." (PMID 30112104, 2018).
liver fibrosis (2 papers, 2017 to 2025). "The results showed that the phosphorylation level of GSK3α was significantly reduced after the addition of inhibitors, suggesting that the phosphorylation level of kinase affects the kinase activity and plays an important role in the process of liver fibrosis in mice." (PMID 40368138, 2025). "Our study further validated the aberrant activation of STK4 (serine/threonine-protein kinase 4), GSK3α (glycogen synthase kinase 3α), and CDK11B (cyclin-dependent kinase 11B) in liver fibrosis mice and found that their small-molecule inhibitors have antihepatic fibrosis effects." (PMID 40368138, 2025). "•Three dysregulated kinases, STK4, GSK3α, and CDK11B, were screened out in mouse liver fibrosis." (PMID 40368138, 2025).
lung adenocarcinoma (2 papers, 2016 to 2022). A carcinoma that arises from the lung and is characterized by the presence of malignant glandular epithelial cells. "Also, the aberrant overexpression of GSK-3α was associated with a shorter survival time especially in patients with lung adenocarcinoma." (PMID 27049759, 2016). "Results showed that GSK3α was significantly upregulated in both lung adenocarcinoma, lung squamous carcinoma and various cancer, relative to adjacent normal tissues." (PMID 35292059, 2022).
myocardial infarction (2 papers, 2020 to 2022). Gross necrosis of the myocardium, as a result of interruption of the blood supply to the area, as in coronary thrombosis. "These contrasting results related to GSK3α biological effects have also been reported in cardiomyocytes after myocardial infarction (MI), where KO germline models have demonstrated deleterious effects in cardiac functions, while cKO postnatal models have been reported to be protective." (PMID 33339170, 2020). "GSK-3β-specific deficiency dramatically inhibits apoptosis after myocardial infarction (MI), and conditional deletion of GSK-3α in the heart reduces the Bax/Bcl-2 ratio and apoptosis." (PMID 36036015, 2022).
non-small cell lung carcinoma (2 papers, 2023 to 2026). A group of at least three distinct histological types of lung cancer, including non-small cell squamous cell carcinoma, adenocarcinoma, and large cell carcinoma. "In non-small cell lung cancer (NSCLC), epidermal growth factor receptor (EGFR) inhibition activates GSK3α-mediated phosphorylation of PD-L1, which facilitates ARIH1-mediated ubiquitination at K271 and K281, promoting proteasomal degradation." (PMID 41486149, 2026).
osteosarcoma (2 papers, 2021 to 2024). A usually aggressive malignant bone-forming mesenchymal neoplasm, predominantly affecting adolescents and young adults. "Nevertheless, our findings, in contrast to the conventional RAGE-driven AKT activation, demonstrated that CML exposure actually restrained the activation of AKT and GSK3α/β in osteosarcoma cells." (PMID 38250151, 2024). "Intriguingly, our results demonstrated that CML treatment in osteosarcoma cells led to a reduction in the phosphorylation of both AKT and GSK3α/β." (PMID 38250151, 2024).
prostate tumor (2 papers, 2015 to 2016). "However, in mouse prostate tumors, GSK3β levels are higher than GSK3α levels, thus GSK3β may play more important roles than GSK3α." (PMID 26871944, 2016).
acinic cell carcinoma (1 paper, 2015). "The expression of GSK3α was observed more in OSCC tumors than other types of tumors in the oral cavity (such as mucoepidermoid carcinoma, adenoid cystic carcinoma, basal cell carcinoma, adamantinoma, and acinic cell carcinoma considered together) (p = 0.02)." (PMID 25645517, 2015). "The tissue samples of basal cell carcinoma showed very faint expression of both GSK3α and GSK3β (m, n), and acinic cell carcinoma showed no expression (o, p) of either GSK3α or GSK3β." (PMID 25645517, 2015).
acute leukemia (1 paper, 2024). A clonal (malignant) hematopoietic disorder with an acute onset, affecting the bone marrow and the peripheral blood. "The two GSK-3 paralogs, GSK-3α and GSK-3β, have variably been reported to have tumor suppressor and oncogenic properties in different acute leukemia types and subtypes." (PMID 38284896, 2024).
adamantinoma (1 paper, 2015). A low grade malignant neoplasm arising from the long bones. "The mandibular benign adamantinomas showed immunoreactivity to both GSK3α and GSK3β (e, f)." (PMID 25645517, 2015).
alveolitis (1 paper, 2017). "GSK3A/GSK3B inhibition in bleomycin-exposed mice has been shown to reduce alveolitis, lung fibrosis, and alveolar cell apoptosis." (PMID 28440314, 2017).
benign tumors of the mouth (1 paper, 2015). "Although the overexpression of GSK3β and the mild expression of GSK3α were found in various types of cancer and benign tumors of the mouth, the expression was mainly detected in OSCC." (PMID 25645517, 2015).
breast tumours (1 paper, 2021). "Moreover, analyses of TCGA tumour data demonstrated that GSK3α and GSK3β mRNA levels are specifically increased in BRCA1/2-mutated breast tumours, suggesting GSK3 as a potential clinical target for tumours lacking BRCA function." (PMID 34389725, 2021).
cardiac ischemia (1 paper, 2025). "The dominance of TNFα/NF-κB signaling is consistent with previous reports linking GSK-3α to amplified pro-inflammatory responses in cardiac ischemia conditions." (PMID 40836599, 2025).
cardiomyopathy (1 paper, 2025). A disease of the heart muscle or myocardium proper. "A study has shown that GSK-3α promotes fatty acid uptake in cardiomyocytes, eventually leading to lipotoxic cardiomyopathy through phosphorylation of PPARα." (PMID 40836599, 2025).
chronic lymphocytic leukemia (1 paper, 2016). "Jerome Paggetti reported that exosomes released by chronic lymphocytic leukemia could induce an inflammatory phenotype in stromal cells through activating AKT, ERK1/2, CREB, and GSK3α/β signaling pathways." (PMID 27090786, 2016).
colitis (1 paper, 2022). Inflammation of the colon. "The oral GSK3-α/β and CDK9 inhibitor, ABC1183, led to a dramatic improvement in dextran sulfate sodium- and 2,4,6-trinitrobenzene sulfonic acid- induced colitis that was associated with suppression of TNF-α and IL-6, and no observed organ or hematological toxicity." (PMID 35660024, 2022).